GZMB (granzyme B)
Diseases named in the same sentence as GZMB in open-access papers (continued):
Sharing a sentence is not in itself a finding about the gene and the disease.
tumor (continued). "In addition, we observed significant increase of CD8+ and Granzyme B+ positive cells infiltration in USP5 knockdown tumors, indicating USP5 knockdown could activate anti-tumor immune response." (PMID 34741014, 2021). "Specifically, knockdown of GR increased the percentages of tumor-infiltrating CD8+ cells and granzyme B+ CTLs by 4.6-fold and 2-fold, while treatment with mifepristone increased the percentages of tumor-infiltrating CD8+ cells and granzyme B+ CTLs by 1.9-fold and 1.6-fold." (PMID 34873175, 2021). "Furthermore, the population of granzyme B+, CD8+ in the tumor tissue was significantly increased in the combination group, suggesting that the combined treatment could improve T cell activities in mice." (PMID 34858816, 2021). "However, if we zoom in on the battlefield of tumor immune microenvironment (TIME), granzyme B could be evidenced in most fights." (PMID 33868318, 2021). "Upon antigen recognition, tumor-specific CD8+ T cells have an unsurpassed capacity to eliminate tumor cells through the release of proinflammatory cytokines such as interferon (IFN)-γ and tumor necrosis factor (TNF)-α, and cytotoxic molecules including granzyme B and perforin." (PMID 34571883, 2021). "Likewise, within the CD8+ T cell population, the percentage of granzyme B+ effector CD8+ T cells was significantly higher in tumors of mice receiving anti‐MMR Nb‐IMDQ in comparison to the control group, suggesting an enhanced anti‐tumor immunity." (PMID 34026453, 2021). "However, the expression of granzyme B is not always positively correlated with anti-tumor performance." (PMID 33868318, 2021). "Moreover, AuNP@DCB16F10 + NIR could also significantly inhibit distant tumors and prevent tumor recurrence due to the effective activation of the CTLs, including the CD8+CD69+, CD8+CD107+ and CD8+ Granzyme B+ T cells in tumors and LNs." (PMID 34158866, 2021). "Moreover, immunohistochemical staining showed that the infiltration of CD45 labeled leukocytes in tumor increased under AQB treatment, while the infiltration of CD14 labeled macrophages decreased, as well as the small amount of perforin and granzyme B staining was present in the tumor portion." (PMID 34887871, 2021). "The effect of EGCG treatment on granzyme B expression in CD8 T cells could be independent of its effect on PD-L1/PD-L2 expression in tumor cells and warrants further investigation." (PMID 34832863, 2021). "In addition, previous study showed that selenium nanoparticles could increase the levels of cellular immunomodulatory components (granzyme B, IL-12, IFN-γ, and IL-2) to boost the immune response in mice bearing tumor exposed to crude antigens of 4T1 cells." (PMID 34393797, 2021). "CR intervention also significantly increased the frequencies of tumor-cytotoxic effector T cells (Eff CD8+ and CD4+) in the spleen and peripheral blood, including cytotoxic granzyme B (GrB+) expressing effector T cells in the spleen, such as GrB+CD8+ and cytotoxic GrB+CD4+." (PMID 34707136, 2021). "However, we found that neoadjuvant chemotherapy could only slightly promote the infiltration of immune cells in the overall tumor area, among which the infiltration of CD4+ GzmB+ T cells were significantly increased in NCT group." (PMID 34631551, 2021). "This dichotomy in the response pre‐ and post‐treatment could possibly indicate lack of utilization of the Granzyme B, the effector molecule necessary for tumour killing specifically in the tumour leading to poor overall survival." (PMID 33015859, 2020). "Importantly, the Trm T cell population in the tumor stroma express IFN-γ and granzyme B (GZMB)." (PMID 33240271, 2020). "Functionally, subsequent experiments demonstrated that compound 5d could effectively inhibit tumour cell proliferation, induce apoptosis, up-regulate the expression of IFN-γ and granzyme B, and suppress FoxP3+ Treg cell differentiation, thereby activate the immune system." (PMID 32466694, 2020).
tumor (continued). "Cx43-GJ intercellular communications among NK cells and tumor cells appear to not affect tumor-induced NK-cell degranulation, but to regulate an efficient Ca2+ influx into the target cells, contributing to granzyme B activity and therefore leading to apoptosis." (PMID 32466338, 2020). "Moreover, in a MC38 tumor model, response to anti-PD-1 was dependent on intratumoral cDC1 production of CXCL9 and subsequent signaling through CXCR3 on T cells, which promoted proliferation and production of IFNγ, TNFα, and Granzyme B." (PMID 33584701, 2020). "Collectively, the data suggests that the expression level of GZMB observed in AAs may not be due to an upstream cell regulator, but instead, may have to do with gene expression patterns of the immune cells at the tumor site." (PMID 32983990, 2020). "Similarly, the expression of BTN3A1, CSF2RB, GIMAP7, GZMB, HCLS1, LCP2, and SELL was positively correlated with the infiltration of B cells, CD8+ T cells, CD4+ T cells, neutrophil, and DCs, but was negatively correlated with the tumor purity." (PMID 33042828, 2020). "In addition, similar to CD4+CD25+ Tregs, we found that tumour-infiltrating CD73+Vδ1 T cells could suppress IFN-γ secretion from CD4+ T cells and Perforin and Granzyme B secretion from CD8+ T cells." (PMID 32345959, 2020). "Granzyme B (GrB) is a serine protease produced by a variety of immune, non-immune and tumor cells." (PMID 33262766, 2020). "While COX-inhibitors could suppress PGE2 release by tumor cells, they did not increase the secretion of granzyme B by cytotoxic cells." (PMID 31555275, 2019). "Also, PD-L1241-265-specific CD4+ T-cell line G1 produced granzyme B against HLA-DR-matched tumor cell lines pretreated with IFN-γ (HSC-4 and Lu65), but not against Sa-3." (PMID 31221178, 2019). "We thus hypothesized that CP-31398-induced autophagy improves the lysis of tumor cells through the sequestration/degradation of key negative regulators of the GzmB apoptotic pathway." (PMID 31541080, 2019). "Interestingly, NKG2A− CD8+ T cells secreted a large amount of granzyme B without activation in the normal tissue, but less in the tumor." (PMID 32010126, 2019). "Functional evaluation demonstrated that these KLRG1+CD8 T cells could kill tumor cells in vitro and in vivo in Granzyme B- and Fas/FasL-dependent manners with no tumor antigen specificity, and tend to migrate into tumor sites by high expression of heparanase." (PMID 31664180, 2019). "Tumor cell resistance to granzyme B and how this alters NK cell killing is not clearly defined." (PMID 29925431, 2018). "In addition, a limited number of T cells (CD3+) was present in the tumor microenvironment, with a higher number of regulatory T cells (Foxp3+) and macrophages (Cd11b+) as compared to a low infiltration of activated cytotoxic T cells (CD8+/ Granzyme B+)." (PMID 30458852, 2018). "In keeping with this, no data are available so far describing whether granzyme B is selectively degraded by autophagy or it is just an “innocent victim” subjected to non-specific degradation under hypoxia in tumor cells." (PMID 29922284, 2018). "Finally, we monitored by flow cytometry, the expression of Granzyme B (GrB) by CD8+ T cells isolated from the tumor of SVX-vaccinated or not vaccinated mice." (PMID 30483475, 2018). "Granzyme B (GZMB) expression in tumor neutrophils has not been studied." (PMID 29983866, 2018). "This loss of control correlated with markedly reduced tumor infiltration by CD8+ T cells and the fact that the few infiltrating CD8+ T cells, including tissue-resident memory T cells (TRM) identified by CD103 expression, did not express granzyme B (GzmB)." (PMID 29429633, 2018). "In bortezomib-treated 4T1HA tumor-bearing mice, CD4+T-cells showed increased IL-2 production, CD11c+ dendritic cells showed increased IL-12 and IL-15 production, and HA-specific activated CD8+T-cells showed enhanced expression of IFNγ, granzyme-B and transcription factor eomesodermin." (PMID 28052005, 2017).
tumor (continued). "We show that an elevated STAT1 transcriptional response is associated with a robust increase in GZMB (13-fold), CD8A (4.3-fold) and PD-L1 (2.6-fold) expression levels in STAT3Low tumours but not in STAT3High tumours (1.9-fold, 1.4-fold and 1.1-fold, respectively)." (PMID 28276425, 2017). "Importantly, expression of key effector molecules that directly induce CD8+ Tc-mediated tumour killing, such as perforin and granzyme B, was not changed by co-incubation of CD8+ Tc with aTreg." (PMID 28504276, 2017). "Bortezomib administration increased IFNγ and granzyme-B expression on Vβ8.1/2+CD8+T cells in tumor-bearing mice even in the presence of IL-12 and IL-15 neutralization antibody treatments, and restored them to the levels comparable to tumor-bearing mice treated with bortezomib only." (PMID 28052005, 2017). "We confirmed that in the brain of EE mice, there is an increased frequency of NK cells expressing granzyme B and IFN-γ, and this leads to an increased degranulation of NK cells ex vivo (not shown) which was further increased when challenged against tumor cells (GL261 and YAC-1 cells)." (PMID 29286001, 2017). "The ratio of intra-tumoral granzyme B+CD8+ T cells (CTLs)/live Treg cells was also significantly higher in the group receiving combination treatment than in the vehicle control and single-agent groups, strongly indicative of an ongoing anti-tumor immune response." (PMID 28920002, 2017). "Supporting the protumorigenic roles of FcγRIIlow/− B cells, high infiltration of FcγRIIlow/− B cells in HCC tumours positively correlated with dysfunction of tumour-derived CD8+ T cells with impaired capacities for production of proinflammatory TNF-α and IFN-γ and cytotoxic granzyme B and perforin." (PMID 27853178, 2016). "Consistent with this, we also observed that high infiltration of FcγRIIlow/− B cells in HCC tumours positively correlated with increased dysfunction of CD8+ T cells with impaired capacities for production of proinflammatory TNF-α and IFN-γ and cytotoxic granzyme B and perforin." (PMID 27853178, 2016). "In line with this possibility, the over-expressed genes in LumA-R2 samples included genes typical of CTLs (and also natural killer (NK) cells), which may lead to anti-tumor cytotoxic activities exerted by the granzyme (GZMA and GZMB) and perforin pathways (PRF1)." (PMID 27386846, 2016). "IL-17 was the signature cytokine of Th17; researches showed that IL-17 could enhance the cytotoxic effects of NK cells against tumor cells by augmenting the expression of cytotoxic molecules including tumor necrosis factor-α (TNF-α), interferon-γ (IFN-γ), Perforin, and Granzyme B." (PMID 27722177, 2016). "However, granzyme B expression levels in the tumor tissues (10.6 ± 4) were not significantly higher than the controls (6.1 ± 1.8)." (PMID 25605488, 2015). "Collectively, the increased population of CD44hiCD8+ T cells in DC-immunized SKAP55−/− mice or ADAP−/− mice, which decreased PD-1 expression (but not CTLA-4) and increased granzyme B levels, might enhance the protection against tumor formation." (PMID 25851535, 2015). "It is also possible that CD4+ T cells could themselves directly kill tumor cells, e.g., through FasL/Fas interactions, similar to what has been described for killing of MHC IIPOS B lymphoma cells, or a perforin/granzyme B-dependent mechanism as described for killing of the MHC IIPOS B16 cells." (PMID 24782871, 2014). "In contrast to classic CD8+ Tc cells, Tc17 cells are negative for granzyme B as well as perforin and lacking cytolytic activity in vitro, and the absence of Eomes in tumor infiltrating lymphocytes is correlated with enhanced lymph node metastasis in colorectal cancers." (PMID 24523865, 2014). "We demonstrated that Granzyme B-generating CD4+ and CD8+ T cells were significantly enhanced in mice that were immunized with scFv-MTBHsp70-bound tumor cells, as compared to those in the mice immunized with tumor cells alone, MTBHsp70-bound tumor cells, or saline." (PMID 24565018, 2014).
tumor (continued). "Importantly, we demonstrate that in vivo depletion of regulatory T cells (Tregs) and CD8+ T cells in FBL-3-bearing DEREG transgenic mice augments IL-2 and GzmB production by CD4+ T cells and increases FV-specific CD4+ T-cell effector and cytotoxic responses leading to the complete tumor regression." (PMID 22890822, 2013). "As a first step in this direction, here we expressed a chimeric granzyme B fusion protein in human NK cells that carries the peptide ligand TGFα for targeting to EGFR, and evaluated its effect on natural cytotoxicity and its cell killing activity towards EGFR-expressing tumor cells." (PMID 23573299, 2013). "The T cells isolated here not only specifically recognised peptide-pulsed or antigen-transfected cells in the context of HLA-A*0201, but also released granzyme B when recognising HLA-A*0201+ ET expressing the antigen, while other HLA-A*0201+ tumour lines and HLA-A*0201 negative ET were not affected." (PMID 21407224, 2011). "For example, FasL and TRAIL do not effectively signal apoptosis in some tumour cells, and therefore targeting the perforin/granzyme-B mechanism may be essential to immunological antitumour activity in these cases." (PMID 17311012, 2007). "This extremely rapid type of cell death is not mediated by the death inducing ligands CD95L, TRAIL and TNF but by perforin and granzyme B. Surprisingly, neither mitochondria nor any of the known caspases appear to be involved in this type of tumour cell killing." (PMID 11875749, 2002). "Moreover, TFMP can neutralize the acidic tumor microenvironment, while the released Mg2+ and TEPP‐46 further augment T cell activation and mitochondrial function, thereby increasing the production of ATP and granzyme B, which effectively eliminate residual tumor cells." (PMID 41178512, 2026). "In addition, the tumor-infiltrating CD8+ T cells within the S100a1KD tumors demonstrated enhanced effector activity compared to those in the scramble control, as shown by their ability to secrete interferon-γ (IFN-γ), granzyme B (GZMB) and tumor necrosis factor-α (TNF-α)." (PMID 40090947, 2025). "Moreover, 9D9 mAb increased the proportion and absolute number of CD8+ T cells producing granzyme B. Thus, reduced Treg function and increased CD8+ T cell effector function could also contribute to the remodeling of the tumor vasculature and the increase of TA-HEVs during anti-CTLA-4 therapy." (PMID 40460830, 2025). "Interestingly, in contrast to the reported mechanisms inducing pyroptosis in tumor cells,[23c] we found that granzyme B may induce hepatocyte pyroptosis by acting on GSDMD but not GSDME." (PMID 39494472, 2025). "Interestingly, ORMDL3 expression showed a negative correlation with CD8+ T cell activation markers such as PRF1, GZMA, and GZMB, as well as with ISGs such as CCL5 and CXCL10, validating our finding that ORMDL3 serves as a negative regulator of the IFN signaling pathway and anti-tumor immunity." (PMID 40126553, 2025). "Furthermore, the expression of GZMB and GNLY could indicate a state of chronic activation of CD8+ T cells, which could lead to exhaustion and dysfunction of T cells, hindering their effective role in eliminating tumor cells." (PMID 40182035, 2025). "Finally, tumor killing assay and ex vivo data from human peripheral blood mononuclear cells and autologous dendritic cell-T cell co-culture demonstrated that VSTM2A significantly enhanced immune activation via the release of granzyme B and interferon (IFN)-γ cytokines." (PMID 39289872, 2024). "Interestingly, high levels of Axl+ CD45+, CD45+ CD8+ and Axl+ CD31− alpha-smooth muscle actin (αSMA)− CD45− (tumor cells) did not correlate with survival probability but increased the infiltration of CD45+ Granzyme B+ associated with an increased survival probability." (PMID 38673795, 2024).
tumor (continued). "Lower granzyme B, at least by some NK cell subsets, besides higher CXCR3 expression per total NK cells collectively suggest that NK cells in BC have a potency to be recruited to the tumor site, but these cells, or at least some of their subsets, may not be able to render their cytotoxic effects." (PMID 38652012, 2024). "In an independent study, eliminating CD4+ T cells or NK1.1+ NK cells individually did not impair tumor response to DCP-IL-12/FLT3L treatment, and disrupting CD4+ T cells was associated with compensatory increases in both total and activated (IFNγ+ or GZMB+) CD8+ T cells." (PMID 37996514, 2024). "Furthermore, antitumor immunomodulatory effects in tumor-bearing hosts have been demonstrated; a decrease in Tregs and MDSCs and an increase in CD8+ T cell-producing IFN-γ and granzyme B was shown, suggesting that the combination of ICIs and CD36 inhibitors may have synergistic effects." (PMID 39273384, 2024). "Besides, the assessment of cytotoxic markers, Perforin and Granzyme B, in OT-1 CD8 + T cells showed that the upregulation of UPP1 in tumor cells significantly reduced the cytotoxicity of OT-1 CD8 + T cells, while this killing ability could be partially restored by blocking PD-L1." (PMID 38331898, 2024). "Additionally, the PCSK9 inhibitor combined with CD137 costimulation could slow tumor growth with enhanced recruitment of CD8+ and GzmB+ CD8+ T cells and reduction of Tregs in a syngeneic mouse model, providing a novel perspective of therapeutic strategies for future research and clinical practice." (PMID 37025995, 2023). "However, treatment of ITF2357, I‐BET151, or JQ1 only on T cells directly isolated from the OT‐I mouse spleen did not increase the secretion levels of IFNγ, GZMB, or TNFα, suggesting the drug effects are dependent on the interaction of T cells with the tumor or other stroma cells in the organoids." (PMID 37271874, 2023). "Although granzyme B is essential for the induction of tumor cell death by cytotoxic T or NK cells, and a low expression may hence impair the host immune response to tumor cells, an overexpression likewise may have negative consequences on patient prognosis as suggested by our results." (PMID 37894418, 2023). "In addition, the proportions of CD69+ or effector molecule granzyme B (GZMB)+ cells among tumour-infiltrating CD8+ T cells were higher in irradiated TRIM21-KO tumours, indicating the IR-induced activation of the CD8+ T-cell antitumour immune response in TRIM21-KO tumours." (PMID 36797289, 2023). "However, TGF-β, produced by tumor cells acts as an immunosuppressive factor that helps cancer cells escape from the immune response by inhibiting the expression of molecules involved in the CTL-mediated tumor cytotoxicity such as perforin, granzyme A, granzyme B, Fas ligand, and IFN-γ." (PMID 37958417, 2023). "A recent study demonstrated that LSD1 ablation does not increase the expression of Granzyme-B (a cytotoxic factor) and Ki-67 (a proliferation marker), but significantly promotes the infiltration of T effector cells into the melanoma cells and then restrains tumor growth." (PMID 37483603, 2023). "Similarly to tumor-infiltrating T cells, splenic CD8+ and CD4+ T cells in mice treated with the combination of AHCC® and DICB had increased expression of Ki-67 and CTLA-4 while granzyme B expression in splenic CD8+ and CD4+ T cells were barely detected by flow cytometry." (PMID 35514996, 2022). "Furthermore, the CD8+ T-cells (CD45+, TCRβ+/CD8+, CD4−) expressed greater amounts of granzyme B molecules in the CpG group and CpG/aOX40 group, compared to the isotype treated tumors, suggesting that the specific treatments increased CD8 T-cell functionality and ability to initiate tumor killing." (PMID 35760778, 2022).